BCL2 (BCL2 apoptosis regulator)
Diseases named in the same sentence as BCL2 in open-access papers (continued):
Sharing a sentence is not in itself a finding about the gene and the disease.
cancer (continued). "Apart from limiting the expression of IAP family proteins, curcumin promotes the apoptosis of cancer cells by increasing the expression of Bax while downregulating the expression of Bcl-2 in various cancer cells." (PMID 34299604, 2021). "The Bcl-2 protein plays a central role as a protector of apoptosis, helping cancer cells escape cell death." (PMID 34221974, 2021). "For example, it is well established that most cancer cells overexpress anti-apoptotic proteins BCL-2, BCL-xL or else MCL-1." (PMID 33920941, 2021). "Bcl-2 is a well-recognized gate-keeper, preventing the cellular death of cancer cells by inhibiting BAX." (PMID 34631119, 2021). "Bcl-2 inhibitors have been used against several cancers and provide a pre-clinical platform for testing novel therapeutic drugs." (PMID 34638779, 2021). "On the contrary, the TQ suppressed anti-apoptotic protein, namely, Bcl-2, was markedly upregulated when cancer cells were co-administrated with TQ and NAC." (PMID 34512159, 2021). "In cancer cell lines BCL2 overexpression seems able to promote cell migration, increasing metastatic potential, by regulating Ca2+ homeostasis and by indirectly inducing the production of MMP-9, able to detach leukemic cells from their extracellular matrix." (PMID 33596632, 2021). "Most recently, it was shown that the inhibition of Bcl2 potentiates cancer cells to the M1 vector via upregulation of BCL2 antagonist/Killer 1 (Bak)." (PMID 34298694, 2021). "Overexpression of BCL2, an antiapoptotic protein, provides the advantage of prolonged survival to cancer cells." (PMID 33976278, 2021). "Adenosine-5′-triphosphate (ATP)-responsive nanoparticles containing a copper complex CTND and B-cell lymphoma 2 (Bcl-2) small interfering RNA (siRNA) were constructed to cope with the resistance of cancer cells to the complex." (PMID 34163720, 2021). "To provide structural information of the intact human Bcl-2 membrane protein, a prime target in understanding cancer and treatment resistance, we have developed an NMR-based strategy as presented here." (PMID 33800399, 2021). "Noticeably, these anti-cancer drugs developed for oncogene-addicted cancers were re-discovered as senolytics: the Bcr-Abl kinase inhibitor dasatinib, the Bcl-2/BclxL inhibitors Venetoclax (ABT-199) and Navitoclax (ABT-263) and Hsp-90 inhibitors (geldanamycin)." (PMID 34504654, 2021). "High expression of B-cell lymphoma/leukemia 2 (Bcl-2) in various human cancers mediates the resistance of cancers to a wide range of 5-fluorouracil and cisplatin treatments." (PMID 33810184, 2021). "The consequent increased BCL-2/BAX ratio results in cancer cell evasion of apoptosis by inhibiting activity of the MPTP and MOMP and increasing Δψm." (PMID 33531986, 2021). "An increase in the expression of bax and decreased expression of bcl-2 in cancer cells, MUG-Mel2 and SCC-25, was observed." (PMID 33920669, 2021). "For instance, the co-treatment of MDA-MB231 cells with leptin and cAMP elevating agents (8-pCPT-2′-O-Me-cAMP, 8-Br-cAMP) blocked the proliferative effect of leptin and induced apoptosis in cancer cells by downregulating Bcl2." (PMID 34588926, 2021). "Performing ROC analyses to define the best cut-off to identify significant patient survival differences across cancer subtypes revealed a clear correlation between higher BCL2 expression levels and a superior RFS." (PMID 34903710, 2021). "Some cancer cells that overexpress BCL2 can escape apoptosis by binding or sequestering pro‐apoptotic factors." (PMID 33838016, 2021). "PARP, Bcl-2, and cyclin D1 present essential functions in the apoptosis and cell cycle and have always been observed with high expressions in various cancers." (PMID 34239588, 2021).
cancer (continued). "Cancer cells acquire resistance to chemotherapeutics, and resistance is in-part conferred by the upregulation of Bcl-2 protein expression, inhibiting apoptotic signals." (PMID 33804830, 2021). "The parent Bcl-2 protein is an apoptosis suppressor that is found to be frequently overexpressed in cancer cells, and the therapy-resistant cancer phenotype is commonly induced by the overexpression of anti-apoptotic Bcl-2." (PMID 34830153, 2021). "Bcl-2 protein can inhibit apoptosis, which promotes the survival of cancer cells and the generation of chemoresistance." (PMID 34259934, 2021). "Increased Bax/Bcl-2 ratio reflects the condition of increased pro-apoptotic Bax to an anti-apoptotic molecule of Bcl-2 in cancer cells." (PMID 34844644, 2021). "The treatment with essential oil indicated mitigation of cancer activity by aborting the mRNA of pro-apoptotic markers such as BCL-2, CASPASE-3, CYP-1A1, and NFκB." (PMID 35009072, 2021). "This investigation summarizes the potential of Bcl-2-inhibitors in the treatment of cancer and novel plans to utilize these inhibitors in pre-clinical and clinical trial applications." (PMID 34638779, 2021). "Our results showed that primaquine induces the apoptosis of cancer cells by reducing c-Myc and Bcl-2 expression." (PMID 34884765, 2021). "Venetoclax is a highly selective and effective B-cell lymphoma-2 (BCL-2) inhibitor, which is able to reinstate the apoptotic potential of cancer cells." (PMID 34073976, 2021). "In the first, a BH3 mimetic is chosen based on the known BCL-2 dependency of the cancer cells to prohibit this defense against the chemotherapy of choice." (PMID 33637708, 2021). "The significance of this research is to find lead compounds for BCL2 inhibitors, which lay the foundation for drug development and compound improvement in cancer drug treatment." (PMID 34259934, 2021). "Studies showed that stabilization of BCL2 G-quadruplexes upon ligand binding inhibits BCL2 expression and induces apoptosis, thus showing anti-cancer effects." (PMID 33638996, 2021). "As there was an increase in the proliferation in cancer cells and mammospheres after fractionated irradiation, we further assessed apoptosis and the expression of anti- and proapoptotic genes, BCL2 and BAX." (PMID 33419140, 2021). "BCL-2 is overexpressed in 80% of ER+ cancers and inhibitors have already been investigated for HR+ cancers in clinical trials." (PMID 33672646, 2021). "Abnormal upregulation of pro-apoptotic Bcl-2 is frequently observed in various types of cancer cells such as gastric, colon, breast and lung cancer." (PMID 36046435, 2021). "Pre-clinical data supports the Bcl-2 G-quadruplex (G4)-selective move toward treating cancer and circumventing the limitations of Bcl-2 protein-based therapeutics." (PMID 34638779, 2021). "The 3-chloro analogue showed a significantly potent IC50 value against Bcl-2-expressing human cancer cell lines, with a similar ELISA binding activity to gossypol as positive control." (PMID 34830153, 2021). "ABT-737 is a potent inhibitor of Bcl-2 and Bcl-xL, and its application in cancer therapeutics has been observed." (PMID 34638779, 2021). "miR-34a, another miRNA having BCL2 as a direct target, is silenced through epigenetic mechanisms in many cancers, including PDAC." (PMID 34575852, 2021).
cancer (continued). "All these findings suggested that treatment of AS to cancer cells disrupts the Bcl-2/Bax ratio thus leading to apoptosis." (PMID 34031264, 2021). "For example, threose nucleic acids were found to inhibit anti-BcL-2 (anti-apoptotic protein) by specifically targeting both mRNA and protein expression of BcL-2 in cancer cells." (PMID 34444724, 2021). "It has been recognized that high ratios of Bcl-2/Bax often lead to poor outcomes with decreased rates of complete remission and low overall survival in cancer patients." (PMID 35153759, 2021). "Navitoclax has been widely used in clinical studies for cancer treatment due to its nature as a selective inhibitor of the BCL-2, BCL-XL and BCL-W proteins." (PMID 34575429, 2021). "Others have shown selective HSPA1 knockout to enhance cancer cell immunogenicity and induce cell death in xenografts independent from caspase/Bcl-2 pathway." (PMID 34827586, 2021). "Overexpression of Bcl-2 and underexpression of Bax reduce cancer cell sensitivity to chemotherapy drugs to avoid apoptosis." (PMID 34306145, 2021). "Bcl-2/Bax ratio has been considered as a marker for cell apoptosis, since the decrease of Bcl-2 expression and increase of Bax expression represent cancer cells under apoptosis process." (PMID 33967759, 2021). "These cells showed further compromised viability, showing that Bcl-2 silencing by co-delivered siRNA sensitized cancer cells to DOX-induced apoptosis." (PMID 34771642, 2021). "Bcl-2 is overexpressed in various types of cancer and is a key mediator for chemotherapy resistance." (PMID 33429845, 2021). "In this study, LLF was shown to promote cancer cells’ apoptosis by inhibiting bcl-2 expression and enhancing Bax expression." (PMID 33653412, 2021). "Since Fukuhara and Rowley discovered the BCL-2 protein, evidence has consistently demonstrated that BCL-2 plays an important role in cancer cell growth, metastasis, angiogenesis, and apoptosis." (PMID 33585660, 2021). "Increased understanding of the biomolecular role of Bcl-2 has allowed for investigations into novel therapeutic opportunities, particularly in the treatment of cancer." (PMID 32570722, 2020). "Among these specific apoptosis-related proteins, Bax can promote the apoptosis of cancer cells, while Bcl-2 can interact with Bax to regulate the occurrence of apoptosis." (PMID 33426053, 2020). "This indicates that cancer cell apoptotic priming (on BCL-2, BCL-xL, or both) is necessary to acute paclitaxel sensitivity and it is consistent with the notion that paclitaxel enhances BCL-xL dependency." (PMID 31937780, 2020). "As a result, in surviving cancer cells, drug therapy generates an abnormal BCL-2 balance with high levels of opposite components on each scale." (PMID 32024199, 2020). "Treatment with FKB+doxorubicin increased the ratio of Beclin-1/Bcl-2, and the ratio of Bax/Bcl-2 in AGS cancer cells indicates that FKB+doxorubicin can increase cell death through pro-apoptotic signaling." (PMID 32882870, 2020). "Treatment of S. costus extract decreased the levels of Bcl-2 in all cancer cells, while the level of Bax expression is highly induced after 48 hours of treatment." (PMID 32766303, 2020). "Down-regulation of COX-2 expression can induce cancer cell apoptosis by down-regulating Bcl-2 expression and up-regulating Bax expression." (PMID 32364228, 2020). "The IAP family (e.g., cIAP-1, Survivin and XIAP) and the Bcl-2 protein are anti-apoptotic proteins that, in response to a variety of pro-apoptotic stimuli, aim to prevent apoptosis in cancer cells, where they can be overexpressed." (PMID 32290047, 2020). "It is now known that these Bcl‐2 proteins are often dysregulated in many cancers often with prosurvival members highly expressed or proapoptotic members downregulated, rendering increased survival of cancer cells." (PMID 34766113, 2020).
cancer (continued). "Since many types of cancers become “addicted” to high levels of Bcl-2 and/or XIAP, we propose that drugs that can promote their degradation would be of significant interest." (PMID 32587235, 2020). "We have confirmed that the effect of C5 is better in cancer cell lines where the high expression of Bcl-2 than low expression cell lines." (PMID 32075108, 2020). "For example, TKI promotes Mcl-1 degradation and, in combination with Bcl-XL/Bcl2 inhibitors, induced apoptosis in cancer cells." (PMID 32276600, 2020). "Previously we have described Disarib, as a small molecule inhibitor that can kill cancer cells in a BCL2 dependent manner both ex vivo and in mouse models when it was administered through intraperitoneal route." (PMID 32938954, 2020). "Cancer cells often require increased anti-apoptotic BCL-2 expression to counteract pro-apoptotic stress, a state of increased apoptotic priming." (PMID 32792521, 2020). "BIRD-2 can kill several Bcl-2-dependent cancer cell types, including primary CLL cells and DLBCL cell lines, by provoking intracellular Ca2+ overload." (PMID 32708132, 2020). "BH3-mimetics, inhibitors of specific BCL-2 proteins, are valuable drugs in cancer therapy to amplify mitochondrial-dependent cell death." (PMID 32024199, 2020). "The results demonstrated that the expression of Bax increased and that of Bcl-2 decreased by 48 hours of treatment with the extract, indicating that the S. costus extract plays a critical role in the apoptosis of cancer cells." (PMID 32766303, 2020). "Taken together, the use of a CLK inhibitor is a novel therapeutic approach to sensitise cancer cells to Bcl-xL/Bcl-2 inhibitors." (PMID 33064779, 2020). "As a result, cancer cells, that express elevated Bcl-2 levels, are more chemoresistant to the standard treatments that activate either apoptosis or autophagic cell death." (PMID 32325714, 2020). "As a transcription factor, STAT3 has been reported to promote the expression of cancer-promoting molecules such as Bcl-2, Survivin, and c-Myc." (PMID 32943090, 2020). "New compounds 4a–m showed a range of IC50 values concentrated in the low micromolar range selectively in Bcl-2 positive human cancer cell lines." (PMID 33256166, 2020). "As the caspase cascade plays a regulatory role in the apoptosis of various cancer cell lines, we examined the effect of CP-Mh on the expression of key molecules of the apoptotic signaling cascade, including Bax/Bcl-2 ratio, BID, Casp-9 and Casp-3." (PMID 33158052, 2020). "and their active ingredients (e.g., cordycepin, salidroside, and gallic acid) have been reported to possess anticancer activity by targeting some apoptosis pathways in cancer, such as Bcl-2/Bax, caspases, PI3K/Akt, JAK2/STAT3, MAPK, and AMPK." (PMID 32774302, 2020). "One of the mechanisms proposed for COX-2-induced deregulation of apoptosis is by increasing Bcl-2 expression in cancer cells, an effect that is abrogated by COX-2 inhibitors." (PMID 32850312, 2020). "This study provides supporting evidence that RT and its simplified right-half model compounds TM-(–)-18 and TM-(–)-4a exert an anti-cancer action through Mcl-1 suppression and in part by the decrease in Bcl-2." (PMID 32260280, 2020). "Recently, BH3 mimetics developed to functionally mimic pro-apoptotic BCL-2 proteins were shown to neutralize anti-apoptotic proteins, enabling efficient apoptosis in cancer cells." (PMID 33023187, 2020). "Anti-apoptotic BCL2 proteins are important targets for cancer therapy as cancers depend on their activity for survival." (PMID 32824203, 2020). "The main advantage of venetoclax over other agents is that it has a high binding affinity for BCL-2 receptors and it very selectively inhibits BCL-2, maintaining anti-apoptotic activity in cancer cells." (PMID 32742874, 2020).
cancer (continued). "BH3 mimetics also synergized with other on-target therapies such as inhibitors of oncogenic kinases that often induce upregulation of pro-apoptotic BH3-only proteins BIM, PUMA, or BMF and shifts between BCL-2 prosurvival dependence in cancer cells." (PMID 32722518, 2020). "Early efforts to overcome the anti-apoptotic defense mechanism in cancer were mainly driven by screening libraries of natural products, which yielded several classes of compounds that can inhibit anti-apoptotic BCL-2 proteins." (PMID 32335811, 2020). "The invention of BH3 profiling technology has made it plausible that a means of examining functional BCL-2 protein dependency and its dynamism during cancer development and progression is now available." (PMID 32131385, 2020). "In suppressing the proliferation of cancer cells, apigenin can induce apoptotic cell death via increasing ROS generation, the down-regulation of anti-apoptotic factors Bcl-2 and Bcl-xl as well as the up-regulation of apoptotic factors Bax and Bim." (PMID 33195038, 2020). "Contrarily, acting as antiapoptotic protein, Bcl-2 plays an essential role as a cell survivor enhancer, and its increased expression level gives cancer cells with a selective survival gain." (PMID 33218180, 2020). "Further studies are required to confirm the clinical potential of Bcl-2 inhibitors as single and combinatorial agents for the therapy of chemotherapy-sensitive and resistant cancer." (PMID 32455818, 2020). "Considering this effect, the exploration of anti-apoptotic BCL-2 inhibitors is considered to have tremendous potential for the discovery of novel pharmacological modulators in cancer." (PMID 33251145, 2020). "In conclusion, our results show that lymphocyte apoptosis and Bax/Bcl-2 ratios were higher in patients with OC in stage 4, T4, and N3 tumors, indicating that they play an important role in cancer prognosis." (PMID 32901694, 2020). "More recently, Xiao and colleagues developed PEG-PCL-PLL NPs, incorporating platinum-based chemotherapeutic agents (oxaliplatin and cisplatin) and Bcl-2-targeting siRNA for cancer treatment." (PMID 32532030, 2020). "Venetoclax (ABT-199) was the first-in-class BCL2 inhibitor approved for the treatment of cancer, for patients with R/R CLL." (PMID 32197371, 2020). "It is likely that the role for BCL-2 inhibitors is likely to expand in cancer therapy, and further results are awaited." (PMID 32131385, 2020). "Another promising anticancer peptide is NuBCP9 (FSRSLHSLL), which is able to bind the Bcl-2 protein, highly overexpressed in cancer cells, turning a cell protector into an apoptosis inductor." (PMID 32392811, 2020). "Antiapoptotic members of B-cell leukemia/lymphoma-2 (BCL-2) family proteins are one of the overexpressed proteins in cancer cells that are oncogenic targets." (PMID 32328476, 2020). "From the chart downloaded from UALCAN, some anti-apoptotic BCL-2 proteins are visibly upregulated in some cancers." (PMID 32325691, 2020). "CAFs have also been shown to enhance BCL-2 protein levels in bladder cancer cells via the activation of IGF1/ERβ signaling in cancer cells in vitro and in vivo." (PMID 33080792, 2020). "Contrary to the expression of Bcl-2 mRNA, Bax exhibited low expression in cisplatin-resistant cancer cells, and the P-values were significant at < 0.001." (PMID 33585454, 2020). "At the mitochondrial level, Venetoclax is the first FDA-approved drug in cancer directly targeting the anti-apoptotic Bcl-2 protein to reactivate apoptosis." (PMID 32517101, 2020). "In conclusion, we herein prove that, in addition to acting as a pan-BCL-2 inhibitor, Obatoclax triggers cancer cell apoptosis through an additional mechanism of action that involves suppression of WNT/β-catenin signaling to downregulate survivin." (PMID 32150830, 2020).